CD44 (CD44 molecule (IN blood group))
Diseases named in the same sentence as CD44 in open-access papers (continued):
Sharing a sentence is not in itself a finding about the gene and the disease.
tumor (continued). "Since the role of CD44 and CD24 in tumor metastasis and invasiveness has previously been reported, CSNK1G2 may, in part, contribute to tumor progress." (PMID 33861751, 2021). "We also analyzed the impact of gemcitabine treatment on the expression of several tumor-promoting genes-TPGs (IL8, IL6, CD44 and CD133) as well as CD95L in experimental tumors derived from the PancTuI-luc cell line with two different settings of treatment (palliative and adjuvant)." (PMID 34771621, 2021). "The specific markers that we analyzed include tumor stem cell markers (CD24, CD44), markers of immunosuppression (CD47, PD-L1), markers of cell adhesion (CD49d, ICAM-1), markers of lymphocytes co-stimulation (CD80, CD86), and markers of antigen presentation (MHC class I, MHC class II)." (PMID 34411144, 2021). "MMP9 can bind to CD44 to degrade fibronectin, which leads to the active form of TGF-βreleasing, then TGF-β enhances the conversion of ECs to endothelial mesenchyme and increases the quantity of CAFs to promote tumor progression." (PMID 34988011, 2021). "A large number of subpopulations with enhanced tumor initiating capacity have been identified, especially several markers, including CD24, CD44, CD117, CD133, ABCG, ESA and ALDH, which are widely used in the literature to identify and investigate human epithelial cancer stem cells." (PMID 33923707, 2021). "However, N-cadherin, β-catenin, Snail, and ESM-1 expression levels were increased in RT-R-MDA-MB-231 tumor tissue compared to MDA-MB-231 tumor tissue and were even higher in CD24−/low/CD44+ tumor tissue." (PMID 34502547, 2021). "They found that expression of CD44 was not related to patient sex and age but to tumor differentiation, stage, and site." (PMID 34837915, 2021). "Interestingly, NFkB can be activated by hyaluronan, which is enriched at the tumor margin, through engaging the toll-like receptor (TLR) 4 on the surface of CD44+ glioma stem-like cells." (PMID 33805316, 2021). "The expression of AT1R, ACE, AGT, glutamine synthetase, CD44 and Fzd7 were not significantly changed in the tumor tissues from the captopril treated mice compared to control mice (respectively)." (PMID 34073112, 2021). "TCGA-GBM data analysis has shown that the GSC markers, CD133 and CD44 were significantly upregulated in GBM patient tumours compared to non-tumour tissue." (PMID 34066147, 2021). "As CD44 and VEGF in the tumor periphery of GBM tended to be expressed in a mutually exclusive manner in terms of responsiveness to Bev therapy, we investigated whether a relationship was present between VEGF and CD44 using three GSC lines." (PMID 33543833, 2021). "Furthermore, TGFβ inhibitor significantly retarded tumour formation, while reducing cell migration and invasion abilities, tumour mass, and the number of metastatic foci derived from orthotopically implanted ALDH+ CD44+ CXCR4+ CD24+ subpopulation." (PMID 34247196, 2021). "In addition, the ADAM-10 expression level was increased in RT-R-MDA-MB-231 tumor tissue compared to MDA-MB-231 tumor tissue and was even higher in CD24−/low/CD44+ tumor tissue." (PMID 34502547, 2021). "Prediction model 11, composed of 18F-FDG PET–based radiomic features (Geary’s C measure and long-run low gray-level emphasis) and biological tumor markers (HER2 and CD44), was the preferred prediction model as it showed the highest observed level of overall performance and discrimination." (PMID 33151397, 2021). "In vitro, we confirmed a tumor suppressive role of ITIH5 in CD44 expressing SCaBER cells reflecting the BASQ subtype but not in basal-type HT1376 cancer cells with lower CD44 (variant) expression." (PMID 33924987, 2021). "Therefore, in this study, we isolated CD24−/low/CD44+ cells from RT-R-MDA-MB-231 cells and determined the role of these CSCs in RT-R-TNBC on tumor progression and immune evasion." (PMID 34502547, 2021).
tumor (continued). "The inhibition of the mTOR signaling pathway in tumors by zotarolimus reduced CD44, EGFR, TGF-β, and VEGF expression, which could decelerate the migration and invasion of tumor cells in cancer metastasis." (PMID 34361836, 2021). "The CD44-cytoplasmic domain activated proteins such as ankyrin, merlin, and ERM involve in actin polymerization mediated by ERM proteins results in cytoskeleton rearrangements for tumour invasion and migration." (PMID 34513617, 2021). "Increased levels of CD44, vimentin, and OCT3/4, along with a decreased expression of E-cadherin were found in tumor spheres compared to parental cells, indicating the occurrence of an epithelial mesenchymal transition (EMT) and/or the acquisition of a stem-like phenotype." (PMID 33922104, 2021). "Hyaluronic acid (HA) is a nonsulfated glycosaminoglycan that along with its family members composed of HA receptors (CD44, cluster of differentiation antigen 44; RHAMM, hyaluronan-mediated motility receptor), HA synthases (HAS1, HAS2, HAS3), and hyaluronidases, promotes tumor growth and progression." (PMID 33958632, 2021). "In accordance with scRNA-seq data, the Oxali + anti–PD-L1 combo increased the percentage and/or total numbers of tumor-infiltrating CD8+ and CD4+ T cells, CD107+IFNγ+ CTLs, IFNγ+ CD8+, and TNF+IFNγ+ CD8+ T cells, CD8+CD44+ Teff cells, and CD8+CD44+PD1+TIM-3+ T cells analyzed by flow cytometry." (PMID 33602823, 2021). "Many studies demonstrated that CD44 could present multiple isoforms through variable mRNA splicing and CD44 isoforms play critical roles in tumor initiation and be considered as potential treatment target in CRC compared with CD44." (PMID 33772655, 2021). "CD44 molecules have been reported to be present in three functional stages: Constitutive binding of HA (most of the tumor cells), non-binding or non-binding until activated by physiological stimuli." (PMID 33540535, 2021). "Tumor samples of 40 consecutive patients with adenocarcinoma of the major salivary gland treated with curative intend at one tertiary center were stained with the CSCs ALDH1, BMI-1, CD44, Nanog, and SOX2." (PMID 33009929, 2021). "Several studies have also reported an enhanced expression of the stem cell markers CD44, ALDH1, c-Met, Oct3/4 and SOX-2 in primary tumours of patients with lymph node metastasis compared to those with negative lymph nodes, although the differences were not always statistically significant." (PMID 34831291, 2021). "Emerging evidence suggests that PaCSCs, marked by CD44, CD24, ESA, CD133, or c-Met proteins, characterize a subset of PDAC with distinct stemness features that permit them to drive tumor heterogeneity, metastasis and resistance to the current chemotherapy and radiation." (PMID 35186942, 2021). "The inhibition of the mTOR signaling pathway in tumors by zotarolimus reduced TGF-β, CD44, VEGF, and EGFR expression, which could decelerate tumor cell migration and invasion in cancer metastasis." (PMID 33925400, 2021). "Moreover, immunohistochemistry staining showed that ITPR3, CD44 and Ki-67 were weaker, while IKBa was stronger in ITPR3-silenced tumor tissues." (PMID 33573671, 2021). "In the ALDH1hi cells group, the tumor is dominated by epithelial tumor cells CD44+CD24low, CD326+CD44+CD24−, and CD326−CD49f+, while in the ALDH1low cells group, CSCs of mesenchymal origin and epithelial tumor cells (CD227+CD44+CD24− and CD44+CD24−CD49f+) are predominant." (PMID 34572409, 2021). "The specific binding of HA to CD44 and the possibility of exploiting the EPR effect could provide an option for nanocarrier active tumor targeting, allowing enhanced cancer cell uptake via the HA-CD44 receptor-mediated endocytosis pathway." (PMID 34198955, 2021). "We then examined the distribution of CD44 and PHA‐EVs in the tumour by immunohistochemistry." (PMID 33738083, 2021).
tumor (continued). "We further validated these findings in xenograft tumor tissues using real-time q-PCR, which showed significant reduction in CD133 (fold change 0.41, p=0.002) and CD44 (fold change 0.77, p=0.05) mRNA levels in STIL-silenced tumor, which was further confirmed by IHC, respectively." (PMID 34485108, 2021). "CD44+CD90+ cells were more aggressive and had stronger tumor‐forming capacity." (PMID 33783988, 2021). "Finally, this study for the first time describes a positive feedback loop that couples YB-1 induction and CD44 alternative splicing to sustain the MDR1 and CD44v6 expressions, and CD44v6 is required for the reversion of differentiated tumor cells into CICs." (PMID 33451103, 2021). "There are no direct reports pointing to the involvement of CD44/CD44v+ TEVs in extravasation of the tumor cells." (PMID 33540535, 2021). "Interestingly, p‐Src levels are also reduced upon treatment with Porc inhibitor, possibly reflecting a role of the Wnt target gene CD44 in promoting Src activation and LATS1/2 inhibition in crypts, similar to its function in other cell and tumour types." (PMID 33950519, 2021). "Notably, the abundance of CD44+ and CD133+ cells and the expression of EpCAM, Oct4 and CD54 in GC have been correlated with TNM stage, tumor size, lymphovascular and distant metastases, poor prognosis and low survival." (PMID 34503571, 2021). "The establishment of tumor spheres from this HCC animal model helped to enrich a subpopulation of cells with stem/progenitor features, such as CD44 positivity and multi-drug resistance 1 (MDR1) high expression, which is responsible for the dye-efflux in cytometric evaluations." (PMID 34572776, 2021). "CD44 is upregulated in GBM and the high level of endogenous CD44 leads to inactivation of Merlin, blocking the phosphorylation/activation of LATS 1/2, thus inhibiting its tumor suppression function." (PMID 34948224, 2021). "Notably, only the CD44+CD133+ subset of Caco-2-derived primary tumors had tumorigenic potential in NSG mice, and the tumor growth of CD44+CD133+ cells was faster in secondary xenografts than in primary transplants." (PMID 33994850, 2021). "CD133, CD44, CD34, FOXP3, PDL1, LDH, and VEGF for assessing tumor cell inhibition." (PMID 37305162, 2021). "However, anti-tumor-specific EGFR and CD44 treatments will also activate immune cells for secondary killing in addition to direct inhibition of tumor aggregation or clustering." (PMID 33995681, 2021). "A study found that PD-L1 was highly expressed in CD133+CD44+ colorectal CSCs, and the altered PD-L1 could upregulate the expressions of stemness-related genes to increase CSC self-renewal ability to form tumor spheres." (PMID 34745015, 2021). "TGF-β drives Notch1-mediated EMT to generate ESCC tumor-initiating cells with high CD44 expression and inhibits Notch3 via ZEB1 expression, thereby preventing cell differentiation and allowing pEMT to progression." (PMID 34421348, 2021). "Based on these reports, CD44-CAR T cells induce remarkable tumour growth inhibition in several CD44-positive carcinoma cells and xenograft mice with no reported signs of CD44-CAR T cells mediating toxicity towards healthy tissues." (PMID 34944493, 2021). "Similarly, in breast cancer, IL-6 secreted by tumor cells participates in the initiation of EMT, leading to an enrichment in CSC-like CD44+ cell subpopulation, with mesenchymal phenotype and invasive properties." (PMID 33923958, 2021). "The stem cell marker, CD24 showed no staining in non-tumour tissue and strong staining in all cells of the tumour tissue, while CD44 showed < 10% stained cells in non-tumour tissue and strong staining in most cells of the tumour tissue." (PMID 33906633, 2021). "CD44 is a surface glycoprotein and a common CSC marker in several human tumor entities." (PMID 32588101, 2021).
tumor (continued). "In addition, our data showed that the percentage of total CD44+CD62L+ central memory CD8+ T cells (Tcm) was significantly diminished in EKO mice compared to control mice in both spleens and tumor draining lymph nodes." (PMID 33553191, 2021). "Only 1 of the 16 (6%) CD44-negative patients had a T1–2 tumor, while 22 of the 27 (81%) CD44-positive patients had a T3–4a tumor (p value = 0.35, Fisher’s exact test)." (PMID 33151397, 2021). "Our results suggest that the inhibition of CD44 signaling via TRAF4 and RAC1 may be beneficial in tumor treatment." (PMID 33804427, 2021). "However, to exclude the effects of CSCs, patients in the C1 group also had a higher risk to develop delayed distant metastasis during 5–7 years post tumor resection than those with <2% of CD44+/CD24- CSCs and < 19.5% of CD44-/CD24- tumor cells (the C0 group)." (PMID 34318746, 2021). "The expression of the tumor markers in both models was similar, with an increase in the mRNA levels of Ly6d, Afp, Gpc3, Birc5, and Lyve1 being higher in DEN-treated WT mice compared to MUP-uPA, while that of Cd44 was comparable in both models." (PMID 34439245, 2021). "However, further studies regarding the role of CD44 marker in the CRC metastasis and tumor recurrence after treatment are needed." (PMID 34837915, 2021). "When tumor cells were co-cultured with LC-MSCs directly, we found the level of CD44 but not CD133 in tumor cells increased in all 3 patients." (PMID 33744858, 2021). "Another study has indicated that afatinib (a second-generation tyrosine kinase inhibitor) reduces the self-renewal and invasive properties of HNSCC CSCs in culture by downregulating CD44 and OCT4, inhibiting tumor sphere formation and growth, and inducing radiosensitization." (PMID 35048028, 2021). "As with tumor cell extravasation, there is no evident data suggesting direct involvement of CD44+ EVs in tumor latency." (PMID 33540535, 2021). "In the same cell line, the highly expressed runt-related transcription factor 2 (RUNX2) forms a complex with the overexpressed CD44, thereby activating many metastasis-related genes, including MMP-9, and consequently contributes to tumour sphere formation and migration." (PMID 34944493, 2021). "HA specifically binds to CD44; this property combined to the EPR effect could provide an option for reinforced active tumor targeting by nanocarriers, improving drug uptake by the cancer cells via the HA-CD44 receptor-mediated endocytosis pathway." (PMID 34198955, 2021). "A previous study demonstrated that, in contrast to bulk tumor cells, rare CD133+CD44+ CCSCs are notably distinct at the genomic, morphological and functional levels, showing extensive self-renewal ability in vivo and in vitro and possessing the capacity to produce different cell phenotypes." (PMID 33819194, 2021). "Moreover, the expression level of CD44 was low in TUBO and BALB-neuT tumours and significantly increased in 4T1 and TS/A tumours." (PMID 33257841, 2021). "The authors of this study also showed that breast CSCs with a mesenchymal-like (CD44+/CD24–) phenotype reside at the invasive edge of the tumor, whereas a population of hybrid epithelial-mesenchymal (E/M) CSCs are localized within the tumor interior." (PMID 33681228, 2021). "The role of CD44 in tumours is not well defined, however, elevated levels of CD44 are associated with numerous malignant tumours." (PMID 34944493, 2021). "Concordantly, GSI treatment reduced mammosphere formation and tumour growth from CD44+/CD24low cells but not CD44+/CD24– cells." (PMID 34295896, 2021). "Moreover, HIF-1α/LOX induction and ESM-1 expression, which are involved in tumor metastasis and progression, were enhanced in CD24−/low/CD44+ cells compared to TNBC and RT-R-TNBC cells." (PMID 34502547, 2021).
tumor (continued). "CD44 and RUNX2, as well as the EMT process, play a critical role in tumor metastasis." (PMID 34769497, 2021). "Finally, we determined that LGALS3, CD44, FN1 and EZR were upregulated in both tumour and host stromal datasets." (PMID 32493768, 2020). "CD44 is involved in many important functions such as cell growth, survival, differentiation, and motility, cell-cell adhesion, the regulation of epithelial-mesenchymal transition (EMT), apoptosis resistance, tumor cell metastasis and invasion." (PMID 32434417, 2020). "However, it seems to be more reliable to use CD133 in combination with other markers, such as CD44 as target biomarkers for the isolation of CCSC in both cell lines and primary tumor cell populations as done in our study." (PMID 32927768, 2020). "Intratumoral activation and effector T cell function were also markedly compromised in the absence of NK cells, as revealed by the enumeration of tumor-infiltrating CD44+ CD8+ T cells and IFN-γ-producing CD8+ or CD4+ T cells." (PMID 33220234, 2020). "Nevertheless, we also note that integrin activation appeared as a universal mechanism detected in pre-activation cells of tumor core and periphery, while CD44 and NRP1/2 activity was higher in tumor core and chemokine receptors CCR1 and CSF1R were higher ranked in the tumor periphery." (PMID 33177572, 2020). "Furthermore, as tumor cell adhesion to the ECM is essential for cancer invasiveness, we tested the invasiveness of CD133+CD44+ cells in binding to the ECM." (PMID 32729895, 2020). "Finally, single-cell suspension from tumour tissues was subjected to flow cytometry to assess the liver CSC markers, such as AFP, GPC3, CEA and CD44." (PMID 32203212, 2020). "Moreover, immunohistochemistry was conducted to analyze CSCs markers (CD44 and CD24) and EMT markers (E-cadherin, β-catenin, vimentin, and N-cadherin) in benign breast lesions (control), paracancer tissues, and tumor tissues." (PMID 33282946, 2020). "CD44 expression was not correlated with tumor-specific survival, overall survival, and recurrence/relapse-free survival, but was associated with disease failure from multivariate survival analysis." (PMID 32434417, 2020). "Recently, non-catalytic MMP-9–mediated activation of CD44 was shown to promote tumor cell amoeboid migration." (PMID 32793493, 2020). "Apart from the miR-449a, we have previously demonstrated that ICG-001 could also inhibit the growth of CSC-enriched NPC tumor spheroids via miR-145/SOX2 axis and the NPC cell migration via miR-150/CD44 axis." (PMID 32752071, 2020). "We investigated this phenomenon further, since early tumor growth following injection was not impacted by CD44 expression in the MDA-MB-231 mouse model." (PMID 32455980, 2020). "Furthermore, both CD44 and STAT3 have been shown to crosstalk with matrix metalloproteinases, which are important mediators of tumor angiogenesis." (PMID 33335857, 2020). "Preventing the formation of the active Notch fragment, Notch intracellular domain (NICD) inhibited the proliferation and decreased the number of CD44+/CD24neg/low and ALDH+ BCSC populations via the inhibition of γ-secretase and suppressed growth in in vivo tumor xenografts." (PMID 32883003, 2020). "The main trigger for CD44 upregulation in LS1034 cells are direct fibroblast-tumor cell interactions, because non-contact co-culture approaches in 6-well plates with inserts were ineffective." (PMID 32685007, 2020). "It has been evident that CD44 as a surface biomarker of cancer stem cells (CSCs) and a vital regulatory factor of epithelial-mesenchymal transition (EMT) program is involved in the regulation of tumor initiation and development." (PMID 33303029, 2020). "The protein expression of CD44 and ANKZF1 were low in both normal and tumor tissues." (PMID 33287763, 2020).